WIF1 (Wnt inhibitory factor 1)
Description:
Binds to WNT proteins and inhibits their activities. May be involved in mesoderm segmentation.
Synonyms: WIF-1
Tractability: Small molecule: a structure with a bound ligand is known; it has a high-quality binding pocket. Antibody: UniProt places it where antibodies can reach, with medium confidence; UniProt predicts a signal peptide or a membrane-spanning region; its Gene Ontology location is reachable by antibodies, with medium confidence.
Gene: Protein-coding gene on chromosome 12 (65,050,626 to 65,121,548, reverse strand). Ensembl gene ENSG00000156076.
Subcellular location: Secreted
Pathways (Reactome):
Signal Transduction: Negative regulation of TCF-dependent signaling by WNT ligand antagonists; TCF dependent signaling in response to WNT
Gene Ontology:
Molecular function: protein binding; signaling receptor binding; Wnt-protein binding
Biological process: negative regulation of Wnt signaling pathway; signal transduction
Cellular component: cell surface; extracellular region
Genetic constraint (gnomAD): Loss-of-function variants: 31 observed, 45.29 expected, observed/expected ratio (o/e) 0.68, 90% interval 0.51 to 0.92. The upper end of that interval is the gene's LOEUF score, 0.92, which puts it in group 3 of 6, group 1 being the genes least tolerant of losing a copy. Missense variants: 437 observed, 449.29 expected, observed/expected ratio (o/e) 0.97, 90% interval 0.9 to 1.05. Synonymous variants: 164 observed, 158.1 expected, observed/expected ratio (o/e) 1.04, 90% interval 0.91 to 1.18.
Cancer hallmarks: cell replicative immortality (suppresses)
Homologues: Orthologues: chimpanzee WIF1 (99% identical), macaque WIF1 (98% identical), pig WIF1 (96% identical), rabbit WIF1 (95% identical), dog WIF1 (94% identical), guinea pig WIF1 (94% identical), mouse Wif1 (94% identical), rat Wif1 (93% identical), tropical clawed frog wif1 (82% identical), zebrafish wif1 (69% identical), Caenorhabditis elegans apx-1 (22% identical), Caenorhabditis elegans R05G6.9 (20% identical), and 6 more. Paralogues in human: DLL3 (24% identical), CD93 (23% identical), CD248 (18% identical), DLK2 (16% identical), CRELD2 (16% identical), FBLN7 (16% identical), CRELD1 (15% identical), CLEC14A (11% identical).
Diseases named in the same sentence as WIF1 in open-access papers:
WIF1 is named in the same sentence as 169 diseases in open-access papers, as found by Europe PMC text mining. Sharing a sentence is not in itself a finding about the gene and the disease. The quoted sentences say what the papers report.
lung carcinoma (43 papers, 2009 to 2025). "Clinical studies of WIF1 methylation or downregulation were particularly common in lung cancer; however, it had a weak diagnostic role in the current study." (PMID 28422739, 2017). "WIF-1 is an important tumor-suppressing gene in lung cancer, and its encoding protein WIF-1 can reduce proliferation and promote apoptosis by inhibiting Wnt/β-catenin signaling in lung cancer." (PMID 26182865, 2015). "Rather, aberrant Wnt activity in lung cancer is linked to increased expression of upstream Wnt signaling effectors such as Dvl or decreased expression of Wnt antagonists such as Wnt-inhibitory factor 1 (Wif-1)." (PMID 23621985, 2013). "Hypermethylation of the IL-12RBETA2 and WIF-1 genes can predict COPD evolution towards to lung cancer." (PMID 36837585, 2023). "Studies showed that procainamide demethylated and re-expressed the RARβ2 and p16 genes in urinary bladder carcinoma and breast cancer cells and the WIF-1 gene in lung cancer cells." (PMID 37077808, 2022). "A number of studies have shown that WIF1 is downregulated by hypermethylation of promoter regions in lung cancer tissue, resulting in the abnormal activation of the Wnt signaling pathway and participating in the development of lung cancer." (PMID 35721205, 2022). "Studies showed that EGCG inhibited the methylation of WIF-1 in lung cancer cells and GSTP1 in prostate cancer cells." (PMID 37077808, 2022). "WIF1, as a tumor suppressor, has been observed to be downregulated in several human cancers, such as lung cancer, neuroblastoma, and cervical cancer." (PMID 34775955, 2021). "Hypermethylation of IL-12RBETA2 and WIF-1 has been found frequently in the transition from COPD to lung cancer." (PMID 32733890, 2020). "In this study, the demethylating effect of curcumin leads to restoration of tumor suppressor gene Wnt inhibitory factor-1 (WIF1) expression whose promoter is hypermethylated and silenced in lung cancer cells and tissues." (PMID 31817718, 2019). "A downregulation of WIF1 was widely reported for multiple cancers, such as prostate cancer, breast cancer, lung cancer, and bladder cancer, and was correlated with a more advanced tumor stage." (PMID 29875348, 2018). "SFRP2 and WIF1 promoter methylation was previously suggested to play important roles in Wnt signaling in lung cancer." (PMID 28422739, 2017). "Down-regulation of the expression level of WIF-1 due to its hypermethylated promoter has been reported in bladder cancer, melanoma, lung cancer, and HCC." (PMID 28899352, 2017). "In a 44 case lung cancer study, WIF1 methylated patients had an inferior overall survival and multivariate analysis revealed WIF1 methylation was an independent prognostic factor in overall survival." (PMID 28484252, 2017). "We previously showed that triptolide inhibits the Wnt pathway in lung cancer via overexpression of Wnt inhibitory factor 1 (WIF1), which is silenced in most lung cancers by promoter hypermethylation." (PMID 27400883, 2016). "Promoter hypermethylation and downregulation of WIF1, a secreted Wnt inhibitor that modulates Wnt activity by directly binding to Wnt ligands, is thought to be critical for lung cancer progression and is a prognostic biomarker for patient survival." (PMID 27400883, 2016). "A recombinant plasmid was transfected into lung cancer A549 cells, and the expression of WIF-1 genes was verified by Western blot after transfection." (PMID 26182865, 2015). "In a panel of 12 paired normal and malignant lung tissues derived from 7 wild-type cyclin E transgenes and 5 proteasome-degradation resistant cyclin E transgenes, 10 showed repression of WIF1 in the lung cancers versus adjacent normal lung tissues." (PMID 23621985, 2013). "Dysregulation of canonical Wnt signaling has also been demonstrated in lung cancer, mediated through epigenetic silencing of negative regulators such as SFRP1 and WIF-1 or rare mutations in APC and β-catenin." (PMID 22016777, 2011).
lung carcinoma (continued). "Previous study has also indicated that TP derivative MRx102 upregulated WIF1 in lung cancer cell lines through decreasing methylation at the WIF1 promoter and increasing the unmethylated population in both A549 and H460 cells, exhibiting the inhibitory effect on the WNT pathway." (PMID 39253139, 2024). "An in vitro examination by Zhi Gao in 2009 revealed that EGCG could demethylate the WIF-1 promoter, reinstating expression and potentially attenuating the Wnt signaling pathway in lung cancer cells." (PMID 38879474, 2024). "In addition, overexpression of miR-31 in these cells depletes several other antagonists of Wnt signaling that have potential miR-31 binding motifs, including SFRP1, SFRP4, and WIF-1, which are often silenced in human lung cancer." (PMID 38309281, 2023). "One study among them demonstrated that hypermethylation of WIF-1 (WNT inhibitory factor 1) and IL-12Rbeta2 (Interleukin 12 receptor, beta 2 subunit) promoters commonly arise during the transition of COPD and add the risk for lung cancer development." (PMID 35008971, 2022). "Similarly, WIF-1 protein activates autophagy and suppresses Wnt signaling in lung cancer at the same time." (PMID 34194501, 2021). "Moreover, EGCG reactivates the expression of WIF-1 (Wnt inhibitory factor-1) through promoter demethylation and inhibits cell growth by downregulating the Wnt canonical pathway in H460 and A549 lung cancer cell lines." (PMID 34638721, 2021). "Moreover, EGCG reactivated the expression of WIF-1 (Wnt inhibitory factor-1) through promoter demethylation and inhibited cell growth by downregulating the Wnt canonical pathway in H460 and A549 lung cancer cell lines." (PMID 30881375, 2019). "Interestingly, methylation of WIF1 has been demonstrated as an independent outcome predictor with a negative impact on patient prognosis in different cancers, including leukemia, lung cancer, breast cancer, and colon cancer." (PMID 28484252, 2017). "Importantly, we discovered that MRx102 has the greatest efficacy in lung cancer cell lines with low WIF1 expression." (PMID 27400883, 2016). "Other than that, it is reported that epigallocatechin-3-gallate (EGCG), the major polyphenol in green tea, also demonstrated potential anticancer effects against lung cancer cells through reactivation of the methylation-silenced gene Wnt inhibitory factor 1 (WIF1)." (PMID 27570510, 2016). "Increased expression of Wnt ligands was reported in breast cancer and dishevelled in cervical cancer, while decreased expression of dickkopf-1 was reported in pancreatic cancer, secreted frizzled-related protein 1 (SFRP1) in lung cancer, and WIF1 in cervical cancer." (PMID 27843945, 2016). "By intersecting these top DEGs, we recognized seven genes potentially involved in the pathogenesis of both SSc and lung cancer: SCN7A, AGTR1, WIF1, PRKG2, LTF, AQP4, and COL10A1." (PMID 39744538, 2024). "Similar results were obtained by another study that multiple WNT inhibitory factors including WIF1, FRZB, SFRP1, ENY2, and DKK1 were upregulated in lung cancer cells in A549 after TP treatment." (PMID 39253139, 2024). "Wif1, an important regulator in the WNT pathway, is also a well-known tumor suppressor gene in lung cancer." (PMID 37513116, 2023). "The expression of Wnt inhibitory factor-1 (WIF-1) and Dickkopf-related protein 3 (Dkk-3), two endogenous inhibitors of the Wnt pathway, which are frequently downregulated in lung cancer, were upregulated." (PMID 29534536, 2018). "In PDAC and Lewis lung cancer cells, radiation treatment was shown to repress cell viability and HOTAIR while enhancing WIF-1 (WNT inhibitory factor 1) expression." (PMID 28872613, 2017). "Recently, methylation of Wnt inhibitory factor 1 (WIF1) has also been found in different cancers, including in lung cancer, gastric cancer, and osteosarcoma." (PMID 28484252, 2017).
lung carcinoma (continued). "Similarly, ALKBH5 also suppresses tumor progression in pancreatic cancer, lung cancer, and esophageal squamous cell carcinoma, with downstream targets such as PER1, YAP, and WIF-1." (PMID 35395767, 2022). "Notably, expression of WIF1 is suppressed by promoter hypermethylation of WIF1 in NSCLC cells and tissues, and restoring WIF1 expression inhibits lung cancer cell growth." (PMID 30348169, 2018). "Our finding that upregulated miR-128-3p in NSCLC cells simultaneously suppresses multiple negative regulators of β-catenin and TGF-β signalling, including Axin1, SFRP2, WIF1, SMURF2 and PP1c, provides unique insights in understanding the modulation of the β-catenin and TGF-β pathways in lung cancer." (PMID 28627514, 2017). "Likewise to WIF1, the DKK3 gene was also reported as a frequent target of epigenetic inactivation in numerous tumor entities, e.g. in lung cancer, prostate cancer and leukemia, suggesting that DKK3 may exert tumor suppressive functions." (PMID 19570204, 2009).
breast carcinoma (36 papers, 2006 to 2024). "The WNT signaling pathway plays an important role in development and tissue homeostasis, and its aberrant activation by loss of expression WIF1 or SFRP1 has been shown to be an important early event in breast cancer progression." (PMID 19187537, 2009). "For instance, genes encoding secreted frizzled-related proteins (SFRP) and Wnt-inhibitory factor-1 (WIF1) were previously reported as frequent targets of epigenetic inactivation in breast cancer." (PMID 19570204, 2009). "In a bivariate analysis, WIF1 methylation status in breast carcinomas was significantly associated with the DKK3 methylation status." (PMID 19570204, 2009). "In breast carcinomas, WIF1 methylation was significantly associated with methylation of DKK3 (p = 0.009)." (PMID 19570204, 2009). "The present study investigated the possible anti-cancer effects of nano curcumin (CC-CUR) against different types of breast cancer cell lines by analyzing the expression level of miR-221, miR-222 and β-catenin as oncogene and WIF1 as a tumor suppressor gene." (PMID 38365810, 2024). "WIF1 has been shown to be down-regulated in various human cancers, including breast cancer, and has been regarded as a tumor suppressor gene." (PMID 38365810, 2024). "WIF1 is a member of the Wnt pathway and has been identified downregulating in several cancers, including prostate, bladder, lung, and breast cancer." (PMID 37786775, 2023). "Adiponectin also impedes Wnt/β-catenin-signaling pathways by regulating the expression of WIF1 in human breast carcinoma cells." (PMID 34398360, 2021). "More strikingly, WIF1 promoter hypermethylation has been frequently observed in breast cancer cells, and also serves as an early trigger in the development of hereditary breast cancers." (PMID 33462997, 2021). "A previous study indicated that WIF1 expression is significantly repressed in breast cancer stem cells, which in turn promotes their self‐renewal." (PMID 33462997, 2021). "For instance, DKK3 and WIF1 methylation was detected in a similar proportion of breast cancer patients, but only DKK3 methylation was a prognostic marker of survival." (PMID 32083079, 2020). "We show that Star-PAP and PIPKIα together regulate 3′-end processing and expression of pre-mRNAs encoding key anti-invasive factors (KISS1R, CDH1, NME1, CDH13, FEZ1, and WIF1) in breast cancer." (PMID 29203642, 2018). "And ISL was deemed to enhance WIF1 gene expression via promoting the demethylation of its promoter, which exerted the anti-cancer activity against breast cancer." (PMID 30081934, 2018). "Several Wnt/β-catenin antagonists were epigenetically repressed in breast cancer, including WIF1, SFRP1, SFRP2, SFRP5, DKK1, and DKK3." (PMID 28467796, 2017). "Recent work has provided preclinical evidence that isoliquiritigenin treatment can prevent breast cancer initiation and progression through WIF1 demethylation." (PMID 28484252, 2017). "Examples therefor are the upregulation of the WNT receptor FZD7 found in certain breast cancers and hepatocellular carcinoma or the downregulation of the WNT inhibitory factor 1 (WIF1) found in prostate, lung, breast and bladder cancers." (PMID 27429001, 2016). "Here, we report a novel function of ISL as a natural demethylation agent targeting WIF1 to prevent breast cancer." (PMID 25918249, 2015). "Taken together, our findings discovered a novel function of ISL as a natural DNMT1 inhibitor to prevent breast cancer by targeting the aberrant WIF1 signaling." (PMID 25918249, 2015). "Taken together, our study demonstrated that the dietary compound ISL prevents mammary carcinogenesis by inhibiting breast cancer stem cells through DNMT1-mediated WIF1 demethylation." (PMID 25918249, 2015). "Taken together, our findings not only provide preclinical evidence to demonstrate the use of ISL as a dietary supplement to inhibit mammary carcinogenesis but also shed novel light on WIF1 as an epigenetic target for breast cancer prevention." (PMID 25918249, 2015).
breast carcinoma (continued). "Accumulating evidence has supported that low levels of WIF1 in breast cancer were largely attributed to its aberrant hypermethylation." (PMID 25918249, 2015). "Our findings not only provide preclinical evidence for supporting ISL as a natural chemopreventive agent but also shed novel light on the development of WIF1 as an epigenetic target for breast cancer prevention." (PMID 25918249, 2015). "Both breast cancer cell lines treated with ISL showed dose-dependent elevations of WIF1 transcript levels." (PMID 25918249, 2015). "miRNA-374a promotes breast cancer metastasis by downregulating WIF1, PTEN and WNT5A expression, consequently activating WNT/β-catenin signaling." (PMID 25491321, 2014). "In contrast, epigenetic silencing of APC and Wnt ligand inhibitors (sFRP1 and Wif1) have often been reported in primary human mammary tumors and in human breast cancer cell lines." (PMID 24887235, 2014). "We initially assessed promoter methylation of SFRP1, SFRP2, SFRP5, ITIH5, DKK3, and WIF1 in 112 paired breast cancer tissue and serum samples by using qualitative MSP." (PMID 23320751, 2013). "In contrast, 95 of 150 primary breast carcinomas (63.3%) revealed a methylated WIF1 promoter sequence, as indicated by amplification with primers specific to methylated DNA." (PMID 19570204, 2009). "This study shows that the Wnt antagonist gene WIF1 is frequently inactivated by promoter hypermethylation in human breast cancer." (PMID 19570204, 2009). "Next, WIF1 promoter methylation was determined by MSP in 150 primary breast carcinoma specimens and also in 19 matching normal breast tissues." (PMID 19570204, 2009). "This demonstrates that in spite of a statistical association between methylation of the two genes, there is still a large fraction of breast cancer patients with different DKK3/WIF1 methylation pattern." (PMID 19570204, 2009). "Most important, major differences between WIF1 and DKK3 methylation arise in their association with breast cancer patient survival." (PMID 19570204, 2009). "Since these samples were identical to the samples for which we now have determined WIF1 methylation, we were able to perform a combined analysis of both genes' methylation in breast cancer." (PMID 19570204, 2009). "A recent study of 24 primary breast cancers showed that 67% were aberrantly methylated in the WIF1 promoter; this correlated with decreased expression in tumour samples when compared with normal tissue." (PMID 16933995, 2006). "Hypermethylation of WIF1 promoter was observed in 67% of breast cancer cells, which was mainly due to the cooperative activity of DNMT1 and DNMT3b, suggesting that WIF1 epigenetic silencing could link to Wnt dysregulation and breast carcinogenesis." (PMID 35620052, 2022). "Indeed, epigenetic silencing of SFRP1 and Wnt inhibitory factor 1 (Wif1) has been reported in a significant amount of human breast cancers and was also shown to correlate with a poor disease outcome." (PMID 27355964, 2016). "To confirm our MSP results and determine how ISL affects WIF1 promoter methylation in breast cancer, we used bisulfite sequencing to analyze the methylation status of 39 CpG sites within the 415-bp fragment of the WIF1 promoter (from −555 to −140) in MDA-MB-231 and MCF-7 cells." (PMID 25918249, 2015). "Compared to other suppressors, WIF1 inactivation is a common event in breast cancer." (PMID 25918249, 2015). "It has been reported that aberrant DNA methylation may be one of the earliest events contributing to carcinogenesis, and our data further demonstrated the central role of WIF1 methylation in breast cancer development and prevention." (PMID 25918249, 2015). "To further unravel the potential mechanisms underlying the stimulatory effects of ISL on WIF1 expression, we next investigated whether ISL would suppress WIF1 promoter methylation in breast cancer cells." (PMID 25918249, 2015).